CD38 (CD38 molecule)
Diseases named in the same sentence as CD38 in open-access papers (continued):
Sharing a sentence is not in itself a finding about the gene and the disease.
cardiac hypertrophy (continued). "Taken together, our findings suggest that CD38 and/or non-CD38 ARCs in the myocardium could be targets for the treatment of cardiac hypertrophy." (PMID 26959359, 2016). "Therefore, we hypothesize that CD38 may play an essential role in Ang‐II‐induced cardiac hypertrophy." (PMID 28296029, 2017). "Thus, our results indicated that CD38 deficiency attenuated Ang‐II‐induced cardiac hypertrophy but not affect the cardiac functions." (PMID 28296029, 2017). "Thus, inhibition of CD38 might represent a novel strategy for curing pathological cardiac hypertrophy." (PMID 28296029, 2017). "Thus, CD38 could be a novel target for treating cardiac hypertrophy." (PMID 31919492, 2020). "Thus, CD38 may be a novel target for treating cardiac hypertrophy." (PMID 28296029, 2017). "However, knockdown of CD38 significantly decreased Ang‐II‐induced expressions of ANP and BNP which serve as the markers of cardiac hypertrophy." (PMID 28296029, 2017). "In WT mice, ISO induced myocardial hypertrophy, interstitial fibrosis, and cardiac dysfunction, whereas in CD38 KO mice, ISO failed to induce hypertrophy and cardiac function was preserved." (PMID 26959359, 2016). "Thus, our findings indicate that β-adrenergic stimulation contributes to the development of maladaptive cardiac hypertrophy via Ca2+ signaling mediated by NAADP-synthesizing enzyme and CD38 that produce NAADP and cADPR, respectively." (PMID 26959359, 2016). "The sustained increase in [Ca2+]i induced by ISO leads to cardiac dysfunction and cardiac hypertrophy in CD38 WT mice but not in CD38 KO mice." (PMID 26959359, 2016). "Collectively, these results indicate that deletion of CD38 reduces the hypertrophic response to ISO infusion and preserves cardiac function, and that cADPR-mediated Ca2+ signaling plays a critical role in ISO-induced cardiac hypertrophy and fibrosis." (PMID 26959359, 2016). "However, the role of CD38 in cardiac hypertrophy is not explored." (PMID 28296029, 2017).
ovarian carcinoma (16 papers, 2012 to 2024). A malignant neoplasm originating from the surface ovarian epithelium. "In addition, our analyses show that TILs and diverse immune markers in ovarian cancer are associated with CD38 expression levels." (PMID 32425977, 2020). "Variations in CD38 expression across the immune subtypes of ovarian cancer were noted, with the C2 subtype (IFN-γ dominant) showing the highest levels." (PMID 39272943, 2024). "For example, the frequencies of CD38+HLA-DR+CD8+ T cells were enhanced in TILs compared to PBL in ovarian cancer and colorectal cancer patients." (PMID 34211854, 2021). "Studies showed that CD38 expression correlated with favorable outcomes by enhancing immune infiltration in the microenvironment of epithelial ovarian cancer." (PMID 34868310, 2021). "Together, these results robustly indicated that CD38 is a potential prognostic biomarker for ovarian cancer." (PMID 32425977, 2020). "Correlation of CD38 mRNA expression and clinical prognosis in ovarian cancer with different clinicopathological factors by Kaplan–Meier plotter." (PMID 32425977, 2020). "We further evaluated the prognostic impact of CD38 on the different statuses of immune scores and/or stromal scores for ovarian cancer." (PMID 32425977, 2020). "Different levels of CD38 expression in distinct immune subtypes of ovarian cancer were observed, and the C2 (IFN-γ dominant) type had the highest level compared with the other three subtypes." (PMID 32425977, 2020). "All of the studies hinted that CD38 plays a vital role in remodeling the immune microenvironment, and CD38 deserves further research as an immunotherapeutic target and prognostic biomarker in ovarian cancer." (PMID 32425977, 2020). "Here, we present a study that revealed that CD38 expression levels correlate with prognosis in ovarian cancer." (PMID 32425977, 2020). "The GEPIA database was used to evaluate the correlation of CD38 gene expression with the prognosis of ovarian cancer patients, and this analysis included 424 EOC cases." (PMID 32425977, 2020). "F5-10 Cd38-/- EV are also enriched in Arginase-1, and therefore, may exert inhibitory functions on T cells, as it occurs with small EV found in the ascites and plasma of ovarian cancer patients." (PMID 36353645, 2022). "In both CRLM and OVC the percentage of CD38+/HLA-DR+ CD8+ T cells is increased five-fold and four-fold in TIL compared to PBL in ovarian cancer and CRC patients, respectively." (PMID 25436113, 2014). "Although CD38, BATF2, and HLA-DOB have no statistical significance, they show an increasing trend of expression in ovarian cancer." (PMID 34868310, 2021).
atherosclerosis (15 papers, 2014 to 2025). A disease characterized by the build-up of fatty material and calcium deposition in the arterial wall resulting in partial or complete occlusion of the arterial lumen. "In a follow-up study, it was found that increased autophagy in CD38-deficient myocytes exacerbated coronary fibrosis and atherosclerosis in mice." (PMID 40529366, 2025). "A deficit in NAADP-mediated Ca2+ release from lysosomes caused by CD38 deficiency leads to free cholesterol accumulation in lysosomes, and facilitates atherosclerosis." (PMID 36831262, 2023). "CD38 activation can cause endothelial dysfunction and it increases susceptibility to atherosclerosis." (PMID 34679610, 2021). "CD38 deficiency causes dysregulation of autophagic flux, reducing collagen I degradation in coronary artery myocytes and leading to its deposition around the coronary artery and the progression of atherosclerosis." (PMID 36831262, 2023). "Studies have also confirmed that high doses of NR supplementation deteriorated atherosclerosis and induced systemic inflammation in ApoE−/− mice through increasing hepatic expression levels of CD38 and decreasing SIRT1." (PMID 40143060, 2025). "In both male and female mice, atherosclerosis regression markedly reduced CD68+CD38+ plaque area in the saline and trehalose groups." (PMID 38433753, 2024). "Taken together, these data suggest that the activation of p90RSK induced by radiation plays a crucial role in T-bet-CD38 induction, resulting in immunosenescence and consequent atherosclerosis formation." (PMID 36426217, 2022). "Among the different processes in which miR-199a-5p participate, several targets are implicated in atherosclerosis including ABCA1, ABCG1, Cav-1, HIF1A, CD38, NCOR1, and SIRT1 in human and mouse." (PMID 36407436, 2022). "Flow cytometry analysis with live cells isolated from aorta tissue showed that the CD45+CD86+ (47.7%) or CD45+CD38+ (41.6%) M1 population in atherosclerosis specifically stained with CDg16 compared with the other CD45− cells." (PMID 30846702, 2019). "Our results demonstrated that the free cholesterol egression from lysosomes was profoundly attenuated in the macrophages with deletion of CD38 gene, which resulted in the lysosomal cholesterol accumulation and atherosclerosis." (PMID 26818887, 2016). "The current studies are designed to examine the functional role of CD38/NAADP pathway in the regulation of lysosomal cholesterol efflux in atherosclerosis." (PMID 26818887, 2016). "The role of CD38 in the pathogenesis of atherosclerosis via NAD metabolism remains controversial." (PMID 40529366, 2025). "Moreover, OPG plasma levels were strictly correlated with lymphocytes T CD8+ HLADR+ CD38+, supporting the relationship with immune activation, cytokine production, and atherosclerosis." (PMID 25374442, 2014). "Thus, from the results of basic research, it appears that CD38 may play a dual role, relating to either anti-atherosclerosis or promoting atherogenesis, depending on the change in sirtuin activity or cADPR- and NAADP-mediated Ca2+ mobilization." (PMID 36831262, 2023). "Considering no direct evidence connecting CD38, PTPN11, NOTCH1, TLR7, and KAT2B with the pathogenesis of MMD, their roles in atherosclerosis may also provide a new perspective and direction for future research on the molecular targeted therapy of MMD." (PMID 36605987, 2022).
co-infection (15 papers, 2010 to 2025). "Moreover, activation (CD38+HLADR- subset) of CD8 T-cells was associated with presence of HCV coinfection in a multivariate analysis correcting by HIV-pVL and CD4 counts, drug abuse and gender." (PMID 28323897, 2017). "Data show that HIVUD and coinfection in both T cell subsets have overlapping CD38 expression profiles, which might be caused by HIV-related chronic immune activation even in subjects with controlled viral load." (PMID 23437063, 2013). "Lung granulomas from Mtb/SIV NHP also contained more (p = 0.0528) CD38+ T cells compared to Mtb-only granulomas, suggesting that the Mtb/SIV co-infection is associated with increased T cell activation." (PMID 32730321, 2020). "We are aware that the sample size influenced the statistical significance, but coinfection with HHV-8 may be associated with an immune activation and increase of CD8/CD38/HLA-DR cells in HIV patients on effective ART." (PMID 30567494, 2018). "Analysis of SFV-specific CD8+ T cells demonstrated SFV-only infection to have higher frequency of CD25+CD38+ double positive phenotype, whereas IAV→SFV co-infection had higher KLRG1+CD38+ expression." (PMID 39817772, 2025). "CD38 and HLA-DR expression on CD8 cells, markers of immune activation, are higher in HIV/TB co-infection than in persons with either HIV infection or TB alone." (PMID 20179751, 2010). "Recent studies show expansion of HLA-DR+ and CD38+ CD4+ T cells in PTB and HIV-TB co-infection." (PMID 30231065, 2018). "Next, we determined the expression of the activation marker CD38 on MAIT cells and observed that patients with AHCV/HIV co-infection had increased frequencies of activated MAIT cells in peripheral blood compared to HIV, CHCV and healthy individuals (p = 0.01, p<0.001, p = 0.002 respectively)." (PMID 27416100, 2016). "The enhanced expression of CD38 on MAIT cells of patients with AHCV/HIV co-infection was not further increased during therapy." (PMID 27416100, 2016). "Increased expression of CD38 and CD23 found in CLL patients with viral coinfection could be correlated with activation of B cell, possibly because of antigenic viral stimulation." (PMID 22567048, 2011). "Despite multiple studies demonstrating increased CD38 and/or HLA-DR expression on CD8 T cells in persons with or without HIV co-infection during active TB there are few studies showing declines in these cellular markers of immune activation in response to TB treatment." (PMID 20179751, 2010).
anemia (14 papers, 2016 to 2025). A reduction in the number of red blood cells, the amount of hemoglobin, and/or the volume of packed red blood cells. "A low level of CD38+HSPCs entropy was associated with lower neutrophils and platelets counts, deep anemia and pancytopenia." (PMID 38575672, 2024). "Previously correlated with a high incidence of lymph node involvement, anemia, hepatomegaly, and elevated β2M levels, CD38 expression stands out as a significant indicator of risk." (PMID 39329950, 2024). "As for the incidence of the adverse events, the MAbs targeting CD38 group exhibited a lower risk of anemia but a higher risk of fatigue than the MAbs targeting PD-1/PD-L1 group." (PMID 34488679, 2021). "Therefore, further studies into the underlying mechanisms of CD34 and CD38 expression in inflammatory-related anemia are needed to fully understand their potential usefulness as indicators of anemia severity and associated pathologies." (PMID 37240288, 2023). "Although the available literature on CD34 and CD38 involvement in anemia is limited, and the exact mechanisms underlying the observed differences in CD34 and CD38 levels are not fully understood, the engagement of several factors may already be identified." (PMID 37240288, 2023). "We also detected substantial thrombocytopenia and anemia in CD38-positive B-NHL patients compared to CD38-negative B-NHL patients." (PMID 39805878, 2025). "In conclusion, hematologic toxicities such as neutropenia, thrombocytopenia, and anemia are common in RRMM patients receiving anti-CD38-based combinations with PIs or IMiDs." (PMID 40786241, 2025). "This study is the first to have shown high CD34 and CD38 expression in older adults with anemia of inflammation." (PMID 37240288, 2023). "High levels of ZAP70 and CD38 are associated with reduced survival in CLL patients, especially in those with unmutated IGHV, and CD38 positivity is frequently found in combination with anemia, thrombocytopenia, and leukocytosis." (PMID 40406271, 2025). "Speaking of the association with anemia or thrombocytopenia and CD38 expressions, CLL patients with anemia and/or thrombocytopenia had significantly higher plasma levels of CXCL13 and galectin-9 than patients without these complications (p < 0.05, p < 0.0001, and p < 0.0001, respectively)." (PMID 37946029, 2024). "Relatively high odds ratios were observed for IL-1β (OR = 72.374, 95%Cl 19.688–354.366) and peripheral blood mononuclear cells CD34 (OR = 3.264, 95%Cl 1.263–8.747) and CD38 (OR = 4.398, 95%Cl 1.701–11.906), which together indicates a higher probability of developing anemia." (PMID 37240288, 2023). "The RRs for neutropenia, anemia, pneumonia, diarrhea, and fatigue in the MAbs targeting CD38 group vs PD-1/PD-L1 group by indirect comparison were 1.207 (95%CI 0.94–1.55), 0.566 (95%CI 0.332–0.963), 1.325 (95%CI 0.725–2.419), 0.446 (95%CI 0.102–1.956), and 5.00 (95%CI 1.717–14.56), respectively." (PMID 34488679, 2021). "Hematologic toxicities, particularly neutropenia, thrombocytopenia, and anemia, are common in RRMM patients receiving anti-CD38-based therapies in combination with PIs/IMiDs." (PMID 40786241, 2025). "Both anemia and oxidative stress are known to promote the release of pro-inflammatory cytokines and reactive oxygen species, which can activate immune cells and potentially induce the expression of CD34 and CD38." (PMID 37240288, 2023). "However, the OR values for CD34 (OR = 3.264, 95%Cl 1.263–8.747) and CD38 (OR = 4.398, 95%Cl 1.701–11.906) suggested a significantly higher probability of developing anemia in patients with cut-off values >19.1 ng/mL for CD34 and >1.4 ng/mL for CD38." (PMID 37240288, 2023). "For CD34 and CD38, AUC was moderately high in the tested model, anemic vs. non-anemic (AUC = 0.600, sensitivity 76.8%, specificity 50.0% for CD34, and AUC = 0.657, sensitivity 76.8%, specificity 57.8% for CD38), which indicates their moderate diagnostic utility in patients with anemia." (PMID 37240288, 2023).
chronic myeloid leukemia (14 papers, 2018 to 2025). "This study aimed to assess the impact of the CD34+/CD38- stem cells (SCs) burden in chronic myeloid leukemia (CML) on treatment response and patients’ outcomes." (PMID 34711000, 2021). "For example, the increased expression of the CD38 gene is related to poor prognosis in chronic granulocytic leukemia." (PMID 30949517, 2019). "First, CD34+/CD38− leukemic stem cells (LSCs) derived from patients with the chronic phase (CP) of chronic myeloid leukemia (CML) expressed CD26 at high levels." (PMID 30348967, 2018). "K562 is a chronic myelogenous leukemia (CML) cell line expressing no CD38 as a negative control." (PMID 35765110, 2022).
diffuse large B-cell lymphoma (14 papers, 2016 to 2024). "Elevated expression of CD38 is also found in other hematological malignancies such as germinal center B-like diffuse large B-cell lymphoma (GCB-DLBCL) and its expression has been linked to prognosis in chronic lymphocytic leukemia, acute lymphocytic leukemia, and acute myeloid leukemia." (PMID 32922390, 2020). "Based on these results, daratumumab is being evaluated in a phase 2 clinical trial in patients with CD38‐positive mantle cell lymphoma, diffuse large B‐cell lymphoma, or follicular lymphoma." (PMID 26864107, 2016). "The CD38 expression may vary in diffuse large B-cell lymphoma (DLBCL) associated with chronic inflammation, lymphomatoid granulomatosis, and HHV-8-positive DLBCL." (PMID 36077708, 2022). "Last, but not least, anti-CD38 mAbs are attracting the interest in many other B-cell malignancies expressing surface CD38 including CLL, mantle cell lymphoma (MCL), diffuse large B-cell lymphoma (DLBCL), and transformed follicular lymphoma (FL) (NCT02413489)." (PMID 29387053, 2017).
T-cell lymphomas (14 papers, 2020 to 2025). "Single targeting CD38-CAR T and dual targeting tandem CD38/latent membrane protein-1-CAR T all showed promising cytotoxicity against NK/T-cell lymphoma in in vitro and in vivo pre-clinical experiments." (PMID 38711850, 2024). "Over 50% of NK/T-cell lymphomas are CD38+ and CD38 correlates with aggressive behavior and a worse prognosis." (PMID 35628826, 2022). "However, preliminary studies have suggested potential efficacy in treating CD38-positive T-cell lymphomas, such as nasal-type NK/T-cell lymphoma." (PMID 39742266, 2024). "Furthermore, anti-CD38 antibodies have yet to be investigated in T-cell lymphomas." (PMID 32225002, 2020). "Moreover, non‐invasive CD38 monitoring is expected to have a broader application across different disease states of MM and may be applicable to a range of malignancies with known CD38 involvement, such as NK/T cell lymphoma, T‐cell acute lymphoblastic leukemia, and primary effusion lymphoma." (PMID 38421139, 2024). "Other ADCs and related targeted therapies under investigation for T-cell lymphomas include those targeting CD3, CD70, CD38, and TRBC1." (PMID 39456582, 2024). "Some antigens are shared between B and T-cell lymphomas, such as CD37 and CD38, and no significant fratricide has been seen with CAR-T targeting CD37 or CD38 in preclinical experiments." (PMID 38711850, 2024).